EFEMP2 (EGF-like fibulin extracellular matrix protein 2)
Diseases named in the same sentence as EFEMP2 in open-access papers (continued):
Sharing a sentence is not in itself a finding about the gene and the disease.
EFEMP2 also shares sentences with these, for which no sentence is quoted: aortic aneurysm (10 papers); Marfan syndrome (4); osteoarthritis (4); Autosomal Recessive Cutis Laxa Type 1B (3); connective tissue disorder (3); Aortic dissection (2); ascending aortic aneurysms (2); breast invasive carcinoma (2); cardiac failure (2); dilated cardiomyopathy (2); Loeys-Dietz syndrome (2); malignant glioma (2); ovarian tumor (2); prostate carcinoma (2); abdominal aortic aneurysm (1); Alstrom syndrome (1); amyloid (1); aneurysmal disease (1); aortic valve disease (1); arterial disease (1); autosomal dominant cutis laxa (1); bacterial infection (1); benign ovarian tumors (1); bronchopulmonary dysplasia (1); cardiac disease (1); cardiac hypertrophy (1); carnitine deficiency (1); cerebrovascular disease (1); cervical tumor (1); colon adenoma (1).
A further 33 diseases each share a sentence with EFEMP2 in 1 paper.